LTF (lactotransferrin)
Diseases named in the same sentence as LTF in open-access papers (continued):
Sharing a sentence is not in itself a finding about the gene and the disease.
cancer (continued). "In the present work, we detected some AMPs (LTF, LZ and Cystatin B), which has numerous biological roles, including the modulation of immune responses, and has anti-microbial, anti-viral, anti-oxidant, anti-cancer, and anti-inflammatory activities." (PMID 38402260, 2024). "Similarly, lactotransferrin (LTF) on cancer cell membranes promotes ferroptosis by increasing intracellular iron levels." (PMID 37607902, 2023). "In cancer, LTF has been described to function in an antiproliferative manner." (PMID 37252795, 2023). "Some studies have shown that LTF has an antitumor function and can inhibit the proliferation and metastasis of cancer cells, and the expression of this gene is downregulated in multiple types of cancers." (PMID 35252353, 2022). "In contrast, LTF protein degradation that is mediated by neural precursor cell-expressed developmentally downregulated gene 4 (NEDD4)-like E3 ubiquitin protein ligase (NEDD4L) blocks iron-dependent lipid peroxidation during ferroptotic cancer cell death." (PMID 33117818, 2020). "Similar to TF, LTF functions as a promoter of ferroptosis in cancer cells." (PMID 33117818, 2020). "LTF regulates cellular growth and has a protective role against cancer." (PMID 28974751, 2017). "LTF might be a novel prognostic biomarker for these cancer types." (PMID 38763993, 2024). "In this context, we propose four potential biomarkers, SPP1, LTF, CARL, and PRDX2, for the early detection of MDSC‐dominant cancer." (PMID 39939411, 2025). "While LTF and TUBA3D were identified as significantly downregulated genes, their roles in cancers remain unclear." (PMID 39565059, 2024). "mRNA levels for the cancer progression-related genes HPV16-E6, HPV16-E7, IL6, and MAP7 were significantly downregulated in SiHa cells treated with CLD compared to control cells, while LTF was upregulated." (PMID 37344615, 2023). "Taken together, LTF, ARG1, PGLYRP1, S100A12 and CAMP/LL-37 affect the human immune system at various levels by producing both protumorigenic and anticancer effects in a tissue- and cancer-specific manner." (PMID 36230605, 2022). "Since metastatic spread is frequently found in the late pathological stage, we next analyzed the mRNA levels of LTF in primary tumors derived from TCGA ccRCC patients diagnosed without or with cancer metastasis." (PMID 32244557, 2020). "In TP microglia, the principal regulator LTF is found to regulate TNF, TLR, chemokine, B-cell receptor signaling pathways and processes such as transcriptional misregulation, natural killer cell mediated cytotoxicity, phagocytosis and carbon metabolism in cancer." (PMID 34976314, 2022). "Consequently, in TP microglia, LTF, the significant TF regulator is found to regulate signaling pathways like TNF, TLR, chemokine, B-cell receptor and processes such as transcriptional misregulation, natural killer cell mediated cytotoxicity, phagocytosis and carbon metabolism in cancer." (PMID 34976314, 2022). "The expression of PIGR, DEFB1, LTF, CLU, SCGB2A1 and S100A7, while having a positive role in cancer elimination, were either downregulated or not changed in all or some of the BC subtypes." (PMID 38589404, 2024). "Receiver operating characteristic (ROC) analyses showed that the expression of the LTF and MTORC1 gene set, not the autophagy gene set, could be the useful biomarkers to predict 5-year overall survival rate and cancer progression in ccRCC patients." (PMID 34944711, 2021).
infection (38 papers, 2008 to 2025). The state of being infected such as from the introduction of a foreign agent such as serum, vaccine, antigenic substance or organism. "The protein products encoded by LTF and LCN2 genes were prominently found in the secondary granules of neutrophils and are considered innate immune proteins to fight infection." (PMID 38912048, 2024). "Animals with BRD show decreased expression of genes for hemoglobin and iron-binding proteins and regulators and an increase in genes for iron maintenance proteins (i.e., LCN2 and LTF) that are released from neutrophils as a response to infection." (PMID 33763112, 2021). "LTF also increases the activity of cathepsin G, a known antibacterial enzyme, and broadens its substrate specificity, suggesting that LTF acts in concert with antibacterial neutrophil-derived enzymes in the initial phase of infection." (PMID 29163511, 2017). "However, the LTF protein levels increased in TB++ adult animals suggesting a mechanism by which mycobacteria manipulate host immune response during infection progression to increase Fe availability resulting in higher bacterial growth and transmission." (PMID 27027307, 2016). "Indeed, lowering the stringency of the microarray analysis allowed the identification of over 70 genes, including several genes known to be associated with the mammary gland response to infection, e.g. SOD2, IL1B, LTF, S100A8 and S100A12." (PMID 23324411, 2013). "Similarly, other genes associated with the mammary gland response to infection are expressed at higher levels in SA24T0, e.g. S100A8, S100A12, CXCL10, interleukin (IL) 1B and lactotransferrin (LTF)." (PMID 23324411, 2013). "We further analyzed the GO/KEGG biological process of LTF, the results showed that LTF also played an important role in immune responses, enzyme inhibitor activity and infection, which suggested that the LTF expression of GBM may be associated with immune infiltrates." (PMID 38763993, 2024). "In a broader sense, LTF may be classified as an acute phase protein and acts as an “alarmin,” a small family of proteins released from neutrophils upon infection, and playing an important role in altering immune reactivity upon subsequent, pathogenic encounter, or clinical insult." (PMID 29163511, 2017). "Proteins S100A9, Heme peroxidase, LTF, Cathelicidin and PGLYRP1 were under-represented in TB+ animals when compared to uninfected TB- controls but protein levels increased as infection progressed in TB++ animals when compared to TB- and/or TB+ adult wild boar." (PMID 27027307, 2016). "However, there was no statistical significance between lactotransferrin concentration assessed in the saliva in infected children in comparison with children without infection, but it was slightly higher." (PMID 39684489, 2024). "We stress that KCTD12, TF, LTF, and MPO are host-response proteins; their altered serum-exosomal levels mirror the child’s innate reaction to infection with azithromycin-resistant M. pneumoniae and do not reflect or cause the bacterial mutation that directly confers resistance." (PMID 41451080, 2025).
bacterial infection (8 papers, 2009 to 2025). "Specific substances such as defensins (α- and β- defensins), lactotransferrin, and calprotectin are secreted to fight against bacterial infection." (PMID 39684489, 2024). "Amongst the proteins identified during proteomic analysis that were decreased in CepEVs were DEFA3, LYZ, CAMP, LTF, and BPIFB1, all of which had strong associations with defense response to bacterium (GO: 0042742), as well as the immune response to bacterial infection." (PMID 41550953, 2025). "Lactotransferrin is an iron-binding protein responsible for immunological reactions, while defensins are a family of microbicidal and cytotoxic peptides released in response to viral and bacterial infections." (PMID 19555476, 2009). "During bacterial infection, neutrophils maintain iron homeostasis by releasing LCN2 and lactoferrin (LTF) to sequester free iron and protect the lung from oxidative stress induced by iron and HBA and HBB molecules." (PMID 33763112, 2021).
neurodegenerative disease (3 papers, 2022 to 2024). A disorder of the central nervous system characterized by gradual and progressive loss of neural tissue and neurologic function. "Previous studies have shown that the expression of LTF increases with age and that LTF is implicated in the progression of the pathology of neurodegenerative diseases." (PMID 37168259, 2023). "LTF expression increases with age and is implicated in neurodegenerative diseases." (PMID 39064752, 2024).
adenocarcinoma (1 paper, 2025). A common cancer characterized by the presence of malignant glandular cells. "Although the protein itself is underexpressed in gastric and EAC, high expression of LTF was observed in metaplastic gastric epithelium, and this expression was associated with the development of adenocarcinoma." (PMID 41134301, 2025).
LTF also shares sentences with these, for which no sentence is quoted: Oral Squamous Cell Carcinoma (4 papers); Alzheimer disease (3); renal fibrosis (3); colitis (2); colon carcinoma (2); diabetes (2); Hepatic steatosis (2); immune disorders (2); inflammatory bowel disease (2); ischemic stroke (2); periodontal disease (2); respiratory infection (2); urinary tract infection (2); abscesses (1); acute kidney injury (1); acute lung injury (1); acute respiratory distress syndrome (1); age-related hearing loss (1); allergic rhinitis (1); androgenetic alopecia (1); aplastic anemia (1); astrocytoma (1); atopic dermatitis (1); autoimmune pancreatitis (1); bacterial meningitis (1); bone tumours (1); cervical adenocarcinoma (1); chondrosarcoma (1); chronic gastritis (1); chronic leukemia (1).
A further 63 diseases each share a sentence with LTF in 1 paper.